ACTA1 (actin alpha 1, skeletal muscle)
Description:
Actins are highly conserved proteins that are involved in various types of cell motility and are ubiquitously expressed in all eukaryotic cells.
Synonyms: ACTA; NEM3; ASMA; CFTD; CFTD1; CFTDM; CMYO2A; CMYO2B; CMYO2C; CMYP2A; CMYP2B; CMYP2C; MPFD; NEM1; NEM2; SHPM
Tractability: Small molecule: a structure with a bound ligand is known. PROTAC: ubiquitination databases record sites on it.
Gene: Protein-coding gene on chromosome 1 (229,430,365 to 229,434,789, reverse strand). Ensembl gene ENSG00000143632.
Subcellular location: Cytoplasm, cytoskeleton
Pathways (Reactome):
Cell-Cell communication: Activation of STAT3 by cadherin engagement; Regulation of CDH1 Function
Extracellular matrix organization: Formation of the dystrophin-glycoprotein complex (DGC)
Muscle contraction: Striated Muscle Contraction
Gene Ontology:
Molecular function: protein binding; ADP binding; ATP binding; ATP hydrolysis activity; myosin binding; structural constituent of cytoskeleton
Biological process: skeletal muscle thin filament assembly; mesenchyme migration; muscle contraction; positive regulation of gene expression; skeletal muscle fiber development
Cellular component: actin cytoskeleton; actin filament; blood microparticle; extracellular exosome; extracellular region; sarcomere; stress fiber; striated muscle thin filament; cell body; cytosol; filopodium; lamellipodium; cytoskeleton
Genetic constraint (gnomAD): Loss-of-function variants: 25 observed, 37.48 expected, observed/expected ratio (o/e) 0.67, 90% interval 0.49 to 0.93. The upper end of that interval is the gene's LOEUF score, 0.93, which puts it in group 3 of 6, group 1 being the genes least tolerant of losing a copy. Missense variants: 174 observed, 573.78 expected, observed/expected ratio (o/e) 0.3, 90% interval 0.27 to 0.34. Synonymous variants: 219 observed, 239.33 expected, observed/expected ratio (o/e) 0.92, 90% interval 0.82 to 1.02.
Gene-disease validity (ClinGen):
ClinGen rates the evidence that ACTA1 causes each of these diseases.
alpha-actinopathy (autosomal dominant; autosomal recessive): Definitive. A musculoskeletal system disorder that covers a wide spectrum of phenotypes and is caused by pathogenic variants in the skeletal muscle α-actin gene (ACTA1).
Homologues: Orthologues: chimpanzee ACTA1 (100% identical), guinea pig ACTA1 (100% identical), macaque ACTA1 (100% identical), mouse Acta1 (100% identical), pig ACTA1 (100% identical), rat Acta1 (100% identical), zebrafish acta1a (99% identical), zebrafish acta1b (99% identical), zebrafish actc1a (99% identical), zebrafish actc1c (99% identical), rabbit ACTA1 (98% identical). Paralogues in human: ACTC1 (99% identical), ACTG2 (98% identical), ACTA2 (98% identical), ACTB (93% identical), ACTG1 (93% identical), ACTBL2 (87% identical), ACTR1B (54% identical), ACTR1A (53% identical), ACTRT3 (49% identical), ACTR2 (48% identical), ACTRT2 (48% identical), ACTRT1 (47% identical), and 14 more.
Diseases named in the same sentence as ACTA1 in open-access papers:
ACTA1 is named in the same sentence as 149 diseases in open-access papers, as found by Europe PMC text mining. Sharing a sentence is not in itself a finding about the gene and the disease. The quoted sentences say what the papers report.
nemaline myopathy (50 papers, 2007 to 2025). Nemaline myopathy (NM) encompasses a large spectrum of myopathies characterized by hypotonia, weakness and depressed or absent deep tendon reflexes, with pathologic evidence of nemaline bodies (rods) on muscle biopsy. "The second case involved a 6-year-old boy who was diagnosed with a severe form of a nemaline myopathy and actin accumulation myopathy caused by a mutation in the ACTA1 gene." (PMID 40564727, 2025). "By applying SMPFO to two forms of human nemaline myopathy (ACTA1 and TNNT1 mutations), we reveal significant reduction in the divergence of myofibre subtypes across both biophysical and proteomic behaviour." (PMID 40320980, 2025). "The majority of ACTA1 variants (approximately 74%) are associated with nemaline myopathy; however, an increasing number have been linked to cardiomyopathy and emerging phenotypes such as distal myopathy." (PMID 40428316, 2025). "De novo heterozygous pathogenetic variant in ACTA1 gene, associated with nemaline myopathy, a rare genetic muscle disorder characterized by muscle weakness and hypotonia." (PMID 38671719, 2024). "The majority of these cases encompassed pathogenic RYR1 variants in core myopathy, NEB and ACTA1 in nemaline myopathy, and pathogenic MTM1 variants in CNM." (PMID 38982518, 2024). "In seven patients with nemaline myopathy, the authors identified several causal variants in the ACTA1 gene (in one patient), the LMOD3 gene (in two patients), the PLOD1 gene (in one patient), and the NEB gene (in four patients)." (PMID 37989827, 2024). "ACTA1 encodes alpha-actin 1, the main constituent of the sarcomeric thin filament and are a frequent cause of nemaline myopathies including NEM3." (PMID 35328477, 2022). "Here, we describe ten novel patients with severe nemaline myopathy associated with dominant ACTA1 mutations." (PMID 35810298, 2022). "The clinical manifestations of nemaline myopathy caused by ACTA1 gene mutations is often severe, with the neonate presenting as a floppy infant, sometimes with failure to establish respiration and spontaneous movements." (PMID 33742414, 2022). "For example, ACTA1 L94P and E259V are recessive missense mutations in skeletal muscle α-actin that predispose to nemaline myopathy." (PMID 34600884, 2021). "A nemaline myopathy case with ACTA-1 gene mutation and carnitine deficiency was the first described with evidence of a disorder of mitochondrial fatty acid oxidation." (PMID 33435938, 2021). "A number of researchers have reported that the mutation of the ACTA1 gene is closely related to a variety of human muscle diseases, such as congenital myopathy, disease in striated muscle, and nemaline myopathy." (PMID 34778431, 2021). "Patients homozygous for these ACTA1 mutations have severe nemaline myopathy, but heterozygous parents are unaffected." (PMID 34600884, 2021). "ACTA1 is the causal gene of nemaline myopathy, characterized by an abnormal distribution of muscle filaments resulting in myopathy." (PMID 32236096, 2020). "In subject P16 we observed trisomy 21 in the subject consistent with a preexisting Down syndrome diagnosis, but were also able to identify a likely pathogenic SNV within the ACTA1 gene conferring the additional diagnosis of an inherited nemaline myopathy." (PMID 30293986, 2019). "Efforts are concentrating on the most commonly mutated genes causing nemaline myopathy, ACTA1 and NEB, and descriptions have been published of a variety of knock-in and knock-out mouse models of causative mutations in these genes." (PMID 31228046, 2019). "The commonest forms of nemaline myopathy are caused by mutations in the genes encoding skeletal muscle α-actin (ACTA1) and nebulin (NEB)." (PMID 31228046, 2019). "Mutations in the skeletal muscle actin gene, ACTA1 are responsible for up to 20% of congenital myopathies with a variety of pathologies that includes nemaline myopathy, intranuclear rod myopathy, actin myopathy, and congenital fibre type disproportion." (PMID 29997361, 2018).
nemaline myopathy (continued). "Mutations in ten different genes cause nemaline myopathy: skeletal muscle α-actin (ACTA1), nebulin (NEB), α-tropomyosin, β-tropomyosin, troponin T1, cofilin 2 (CFL2), KBTBD13, KLHL40, KLHL41 and leiomodin 3 (LMOD3)." (PMID 25931053, 2015). "Many mutations in the skeletal muscle α-actin gene (ACTA1) lead to muscle weakness and nemaline myopathy." (PMID 23029319, 2012). "Linkage analysis indicates that mutations in NEB1 account for at least 50% of all nemaline myopathy patients whereas mutations in ACTA1 have been shown to cause approximately 25% of all nemaline myopathy, but 50% of the severe presentations." (PMID 22174871, 2011). "Mutations in the skeletal muscle α-actin gene (ACTA1) cause congenital myopathies including nemaline myopathy, actin aggregate myopathy and rod-core disease." (PMID 22174871, 2011). "Intriguingly, mutations in the homologous region of other actin isoforms, such as skeletal α‐actin (ACTA1), are frequently associated with severe forms of nemaline myopathy, a congenital myopathy characterized by muscle weakness and the presence of nemaline bodies in muscle fibers." (PMID 40490999, 2025). "The clinical manifestations of nemaline myopathy caused by ACTA1 gene mutations is often severe, more rarely, mutations in ACTA1 may cause the intermediate, mild, or typical Forms of nemaline myopathy." (PMID 37525074, 2024). "Consistent with this hypothesis, a premature boy with a congenital form of nemaline myopathy due to mutation in the ACTA1 gene showed decreased LCAR levels in the eighth week of life." (PMID 38136143, 2023). "On the other hand, regarding human cell lines of the disease, recently, two isogenic lines of induced pluripotent stem cells (iPSCs) derived from a patient with severe nemaline myopathy with a dominant heterozygous mutation in the ACTA1 gene have been achieved." (PMID 38136143, 2023). "More rarely, mutations in ACTA1 may cause the intermediate, mild, or typical forms of nemaline myopathy." (PMID 33742414, 2022). "Except NEB gene mutation, ACTA1 gene mutation is the most common one that cause nemaline myopathy." (PMID 33742414, 2022). "Mutations in ACTA1 are the second most frequent cause of nemaline myopathy." (PMID 36233295, 2022). "ACTA1 disease causes 20–25% of all nemaline myopathy, but 50% of severe nemaline myopathy." (PMID 33827624, 2021). "The recessively inherited MYPN-associated nemaline myopathy is histologically characterized by the presence of intranuclear rods, which may be also observed in ACTA1 mutations and in patients with SLONM." (PMID 32456280, 2020). "Mutations in ACTA1 account for ~25 % of nemaline myopathy cases and ~50 % of severe presentations." (PMID 25931053, 2015). "Therefore, in the present study, we aimed at unraveling these mechanisms using muscles from a transgenic mouse model of nemaline myopathy expressing the ACTA1 Asp286Gly mutation." (PMID 23029319, 2012). "Mutations in NEB1 and ACTA1 are the commonest causes of nemaline myopathy." (PMID 22174871, 2011). "Thus this mouse model displays all the hallmark features of nemaline myopathy, with the additional benefit that the mutant ACTA1 protein can be tracked in the presence of WT ACTA1 through the EGFP tag." (PMID 22174871, 2011). "Central and minicores in association with a dilated cardiomyopathy may also rarely been observed in patients with mutations in the skeletal muscle α-actin (ACTA1) gene, more frequently associated with nemaline myopathy." (PMID 17504518, 2007). "Mutations in the ACTA1 gene, more commonly associated with nemaline myopathy, have been recently implicated in an autosomal dominant myopathy with both central and minicores; however, some patients in this pedigree had an associated cardiomyopathy, which is not a feature in RYR1-related CCD." (PMID 17504518, 2007).
nemaline myopathy (continued). "The vast majority (74%) of ACTA1 variants cause nemaline myopathy (NEM), but there are increasing numbers that cause cardiomyopathy and novel phenotypes such as distal myopathy." (PMID 40225930, 2024). "Amino acid mutations in ACTA1 protein are responsible for the congenital myopathies with muscle weakness such as nemaline myopathy (NM), intranuclear rod myopathy (IRM) and actin myopathy (AM)." (PMID 33509264, 2021). "Nemaline myopathy (NM), the most common non-dystrophic congenital disease of skeletal muscle, can be caused by mutations in the skeletal muscle α-actin gene (ACTA1) (~25% of all NM cases and up to 50% of severe forms of NM)." (PMID 23977274, 2013). "The second case was that of a 6-year-old boy with ACTA1-related nemaline myopathy who experienced recurrent tracheal obstruction due to granulomatous tissue formation." (PMID 40564727, 2025). "The distribution of type I and type II muscle fibers were significantly abnormal in patients with nemaline myopathy caused by NEB gene, however, it was basically normal in patients with nemaline myopathy caused by TPM3 gene and ACTA1 gene." (PMID 37525074, 2024). "This is noteworthy because previous studies in mice have shown that increased expression of Actc1 can modify the phenotype of a different model of nemaline myopathy (ACTA1-related NM)." (PMID 38493359, 2024). "Genetic testing identified an ACTA1 mutation and confirmed nemaline myopathy (NM)." (PMID 38659511, 2024). "ACTA1-GFP has been shown to incorporate into sarcomeres of mice and zebrafish, whereas ACTA1D286G-GFP, which has been associated with nemaline myopathy in humans, has been reported to form rod-shaped nemaline bodies in addition to its sarcomere integration." (PMID 35737712, 2022). "The use of a myosin transgene to improve muscle function in an Acta1 mouse model for nemaline myopathy and the use of calcium sensitizers to improve diaphragm function raise interesting perspectives for the future." (PMID 31228046, 2019). "Cardiac involvement is rare in patients with nemaline myopathy, but has been identified in a few patients with defects in ACTA1, MYPN or MYO18B." (PMID 31228046, 2019). "Despite these crucial advances in our understanding of the pathophysiology of ACTA1‐related nemaline myopathy, to date, no cure exists." (PMID 26891371, 2016). "To investigate the origin of nemaline bodies and to uncover the cause of skeletal muscle weakness, we developed overexpression and loss-of-function zebrafish models for ACTA1-related and a loss-of-function model for NEB-related nemaline myopathy." (PMID 25931053, 2015). "As our experimental system overexpressed ACTA1, we examined a model of recessive nemaline myopathy to see if similar cytoplasmic actin aggregates were present." (PMID 25931053, 2015). "A transgenic mouse model was generated expressing an autosomal dominant mutant (D286G) of ACTA1 (identified in a severe nemaline myopathy patient) fused with EGFP." (PMID 22174871, 2011). "The transgenic C57BL/6J;CBA/Ca-Tg(ACTA1.D286G-EGFP) (abbreviated Tg(ACTA1)D286G-EGFP) mice demonstrate structural abnormalities characteristic of nemaline myopathy, decreased activity and muscle weakness." (PMID 22174871, 2011). "In addition, for assessment of differentiation in another hereditary myopathy and a male origin control patient, one clone from an additional third healthy control line (Control3) and one clone from a patient with nemaline myopathy (ACTA1) were also assessed." (PMID 36085325, 2022). "Taken together, all ACTA1 mutations described in the present study either arose de novo or were described in previously reported nemaline myopathy cases, pointing out their causality and pathogenicity." (PMID 35810298, 2022).
nemaline myopathy (continued). "Overall, this study expands the genetic and morphological spectrum of severe ACTA1-related nemaline myopathy, improves molecular diagnosis, highlights the enlargement of the perinuclear space as an ultrastructural hallmark, and indicates a potential genotype/phenotype correlation." (PMID 35810298, 2022). "Dominant mutations in ACTA1 and TPM3 are most frequently associated with nemaline myopathy characterized by early onset and respiratory insufficiency, while recessive forms of nemaline myopathy are most frequently associated with mutations in the nebulin gene (NEB)." (PMID 35980353, 2022). "To further evaluate this novel DNA methylation pattern, we tested the DMPs against our test set of XLMTM samples (n = 2 with missense variants and n = 5 with a LOF variants, i.e. nonsense or frameshift), plus n = 5 patients with another form of severe myopathy (ACTA1-related nemaline myopathy)." (PMID 35844027, 2022). "Cases of nemaline myopathy children have been found with a homozygous ACTA1 null mutation that express no skeletal actin in their muscles." (PMID 29997361, 2018). "Ringbinden fibres, internal nuclei and myofibrillar myopathy pathologies, not typical features in nemaline myopathy or patients with ACTA1 mutations, were frequently observed." (PMID 22174871, 2011). "In conclusion, the Tg(ACTA1) D286G-EGFP mouse models nemaline myopathy both in terms of muscle weakness and abnormal morphology, and as such could be used to understand better the pathobiology of the disease as well as serve as a useful animal model in which to test possible therapies." (PMID 22174871, 2011). "Thus, the Tg(ACTA1)D286G-EGFP mouse model displays the pathological hallmarks of nemaline myopathy." (PMID 22174871, 2011). "The overlap with ACTA1 was only modest: NAA80 individuals exhibited moderate axial hypotonia and proximal muscle weakness, while ACTA1 individuals have overt nemaline myopathy (similarity score of 20)." (PMID 34805998, 2021). "Taken together, the Tg(ACTA1)D286G-EGFP mouse line is an excellent model of both the characteristic pathological lesions and the muscle weakness of nemaline myopathy, similarly to our Tg(ACTA1)D286G models." (PMID 22174871, 2011). "Other causative genes in CRM have been reported (CFL2, ACTA1, and TPM3), although some of them are typically associated with nemaline myopathy, where cores are not present." (PMID 35980353, 2022). "A prime example is nemaline myopathy (NM), the most common non-dystrophic congenital skeletal muscle myopathy that is caused by mutations in six genes that all encode thin filament proteins (TMP2, TMP3, NEB, ACTA1, TNNT1, CFL2)." (PMID 23437068, 2013).